CD24 (CD24 molecule)
Diseases named in the same sentence as CD24 in open-access papers (continued):
Sharing a sentence is not in itself a finding about the gene and the disease.
tumor (continued). "The series of macrophage clusters (including its progenitors’ monoblast and monocyte clusters) was increased by more than 2.5-fold in tumor-bearing mice but was decreased to 80% of normal levels after treatment with CD24-CAR-T cells." (PMID 38242888, 2024). "TAM-derived EVs containing GATA3 increase tumor development and OC cell resistance to therapy via the CD24/Siglec-10 axis." (PMID 38279998, 2024). "Ligand-receptor analysis uncovered several significant interaction channels, including ligands that were distinctively upregulated in the tumor cells such as CD24, VEGFA, DLL3, and DLK1." (PMID 38358826, 2024). "BCSCs expressing CD44+/CD24– have a greater capacity for tumor development in mice, prompting us to examine their expression status by flow cytometry." (PMID 39452867, 2024). "By combining nanospheres and CD24 antibodies to create a unique antiCD24 nanosphere, the CD24/Siglec-10 signaling pathway is blocked, which regulates CD24 degradation and partially recovers the macrophages' capacity to phagocytose tumor cells." (PMID 38279998, 2024). "Drugs specifically targeting IL21-AS1 to interfere with the expression of IL21-AS1 probably lead to specific downregulation of CD24 in tumours." (PMID 38702326, 2024). "Inhibition of the CD24-Siglec-10 pathway also leads to the activation of inflammatory signaling and anti-tumor signaling." (PMID 38242888, 2024). "MCF-7 cells that were CD24-knockout had a significantly lower tumor burden than the wild-type group, according to in vivo xenograft model studies." (PMID 38279998, 2024). "For example, 5.42 μM 5-Fu, 7.34 μM Dox and 1:1 mixture of Dox and 5-Fu (3.27 and 4.98, respectively) were applied to 3D tumor spheroids created with CD24− CSCs." (PMID 38910198, 2024). "For instance, the interaction of CD24 with P-selectin not only promotes tumor cell migration and metastasis but also reveals a mechanism for immune evasion by engaging Siglec-10 on immune cells, thus dampening immune responses." (PMID 38881902, 2024). "By inhibiting the phagocytic function of immune cells, the CD24-Siglec-E axis facilitates tumor survival and progression by allowing cancer cells to escape immune surveillance." (PMID 38881902, 2024). "CD24 has emerged as a lynchpin of tumor progression and a promising therapeutic target for anti-cancer therapy." (PMID 38881902, 2024). "Taken together, our results uncovered a novel mechanism of macrophage-mediated tumor immune escape by YAP through regulating the “don’t eat me” signal CD24." (PMID 38168654, 2024). "This phenotype was demonstrated in SK-N-AS tumors, whose poor expression of CD24 was previously documented in vitro but yielded a dramatic increase in vivo, suggesting that the upregulation of CD24 offered a selective advantage for tumor growth." (PMID 38214542, 2024). "Activation of the CD24/Siglec-10 pathway facilitates tumor immune evasion by suppressing the activity of cytotoxic T cells and macrophages." (PMID 38881902, 2024). "Dual CAR, which targets both BCMA and CD24 simultaneously, should provide better inhibition of tumor relapse." (PMID 38242888, 2024). "All in all, these results indicate that knockdown of CD24 in vivo inhibits the growth of subcutaneous heterograft tumor and reduces the malignant degree of BC." (PMID 38914670, 2024). "By binding the inhibitory receptor sialic acid-binding Ig-like lectin 10 (Siglec-10) on TAMs, CD24 serves as an antiphagocytic or “don’t eat me” signal which helps tumor cells avoid phagocytosis by macrophages." (PMID 38168654, 2024). "Currently, the impact of CD24 expression on patients’ prognosis and tumor progression remains the subject of debate." (PMID 39791710, 2024). "CD24 is highly expressed among various tumor cells, which is closely related to the development of tumors." (PMID 38914670, 2024).
tumor (continued). "A significant decrease in Pearson's correlation coefficient was observed in a dose‐dependent manner in the tumor tissue of CD24−/CD44+ xenotransplanted groups treated with low and high doses of doxorubicin as compared to the untreated groups." (PMID 38522013, 2024). "Firstly, CD24 is often overexpressed in cancer cells, particularly in CSCs, making it a specific target for therapies that aim to reduce tumor recurrence and metastasis." (PMID 38881902, 2024). "Exploring CD24 as a therapeutic target in oncology presents a unique set of advantages and challenges, reflecting its complex role in tumor biology and immune interactions." (PMID 38881902, 2024). "A further investigation, however, revealed that intracellular CD24 inhibits tumor cell invasion and metastasis by impacting the posttranscriptional control of BART via G3BP RNase activity." (PMID 38279998, 2024). "To assess the impact of CD47 and CD24 signaling on the regulation of macrophage-mediated immune response against cancer, we investigated the expression of CD47 and CD24 in different tumor types." (PMID 38971872, 2024). "Through highly expression of CD24, tumor cells interact with Siglec10, which inhibits the activity of macrophages and achieves immune escape." (PMID 38279998, 2024). "We subsequently isolated tumor cells (CD24+Lin−) by flow cytometry and performed gene expression analyses for deeper characterization." (PMID 38835038, 2024). "Inhibition of CD24 resulted in reduced macrophage-dependent tumor growth and extended survival time in vivo." (PMID 39596658, 2024). "CD24-dependent activation of Src is associated with the downregulation of tissue factor pathway inhibitor 2 (TFPI-2), a tumor suppressor gene." (PMID 38360723, 2024). "In this work, we generate CAR-T cells that recognize the CD24 antigen on minimal residual MM cells and can block the “don’t eat me” CD24-Siglec-10 pathway inducing tumor cell clearance by phagocytic macrophages." (PMID 38242888, 2024). "Previous studies have shown that the intracellular localization of CD24 probably impacts tumour phenotypes." (PMID 38702326, 2024). "Blockade of CD47/SIRPα and CD24/Siglec-10 pathways can promote macrophage-mediated phagocytosis of tumor cells." (PMID 38971872, 2024). "Western blot analysis also showed that the CD24 protein level was markedly decreased in sh-IL21-AS1 xenograft tumours." (PMID 38702326, 2024). "The interaction between sialylated CD24 on tumor cells and inhibitory Siglecs on macrophages forms the CD24-Siglecs axis, which serves as a glycol-immune checkpoint, enhancing immunosuppression and promoting tumor growth." (PMID 39791710, 2024). "In more than 70% of cases, tumour cells showed modified scores of 1 or 2 for CD24 and MET expression, indicating their inhomogeneous expression." (PMID 38030594, 2024). "Both genetic ablation of CD24 or Siglec-10 and the monoclonal antibody blockade of the CD24–Siglec-10 interaction enhance the phagocytosis of macrophages to tumor cells, inhibit tumor growth, and prolong overall survival time." (PMID 38787372, 2024). "CD44 and CD24 are commonly used markers for BCSCs, with CD44+/CD24‒ cells representing a stronger tumour stemness." (PMID 38725048, 2024). "One study found that intracellular CD24 increases tumor cell invasion by encouraging cell contractility and encouraging cell adhesion to fibronectin and collagen I and IV." (PMID 38279998, 2024). "One possible disadvantage of CD24-Fc treatment is that macrophages phagocytosis can be blocked by CD24-Fc treatment when it binds to Siglec-10 on macrophages as the recent reports showed that CD24 exerts a novel ‘don’t eat me’ signal in tumor cells." (PMID 39763958, 2024).
tumor (continued). "Genetic parsing of a variety of tumor stem cells has revealed that tumor stem cells contain specific markers, such as CD24, CD44, CD133 and EpCAM, whose importance for the maintenance and activity of tumor stem cells is unclear." (PMID 39744013, 2024). "Significant upregulation in the gene expression level of tumor stem cell markers CD24, CD44, CD133, and EPCAM were also observed in the 3D Mixed organoids compared to both HUH-7 cell line and 3D HUH-7 organoids." (PMID 38773585, 2024). "The blockade of this checkpoint has demonstrated potential therapeutic benefits, revealing a decrease in tumor growth and an increase in the efficacy of other immunotherapeutic strategies when the inhibitory effects of CD24 are neutralized." (PMID 38881902, 2024). "Nuclear SOX2, nuclear or cytoplasmic BMI1, and membranous or cytoplasmic CD24 or CD166 positivity were observed in the tumor cells of AdCC." (PMID 39858584, 2024). "We found that YAP regulated the expression of CD24 and played an important role in the phagocytosis of tumor cells by macrophages." (PMID 38168654, 2024). "Dendritic cells and natural killer (NK)/T cells declined in tumor-bearing mice and continued to decline after CD24-CAR-T cells treatment." (PMID 38242888, 2024). "Further evidence that the CD24/SIGLEC-10 axis functions as a "don't eat me" signal in tumor immunity comes from the finding that inhibition of the CD24/SIGLEC-10 axis can increase phagocytosis more than CD47 blocking therapy." (PMID 38279998, 2024). "The overexpressed tumour targets discussed in this review, CD24, the HMGA protein, and the nucleolin protein, would disclose new horizons for further research related to this disease." (PMID 38975183, 2024). "It has been discovered that a number of cancers highly express sialylated glycans, which bind to Siglec-10 and use the CD24/Siglec-10 interaction to evade the immune system around the tumor." (PMID 38279998, 2024). "According to recent reports, CD24 is involved in the regulation of stem cell properties, enhancing cell adhesion and migration as well as tumor growth." (PMID 39769068, 2024). "The mRNA expression of SPIB, PLK1, and CD24 is upregulated in clinical tumor tissues, whereas NTRK3 and EDA2R mRNA expression is downregulated." (PMID 39596658, 2024). "In the tumor microenvironment, CD24 is an important checkpoint molecule controlling the innate immune response." (PMID 38242888, 2024). "Our animal model data and clinical data show that YAP combined with CD24 in tumor microenvironment redefines the impact of TAMs on the prognosis of ESCC patients which will provide a valuable basis for precision medicine." (PMID 38168654, 2024). "Although CD24 up-regulation has been previously correlated with tumor progression, invasiveness, differentiation, and chemotherapy resistance, its role in modulating the CRC stem cell phenotype remains inconclusive." (PMID 39061234, 2024). "CD24 is a highly glycosylated glycosylphosphatidylinositol anchored membrane protein that plays an important role in tumor progression." (PMID 38914670, 2024). "CD24 is overexpressed in various tumours and considered a regulator of cell migration, invasion, and proliferation." (PMID 38702326, 2024). "The tumour cells at the tip of the papillae and stromal invasion were more intensely and frequently stained for CD24 and MET." (PMID 38030594, 2024). "BSCS subpopulations with the CD44+/CD24- phenotype or high ALDH activity were analyzed to verify the role of NSDHL in maintaining the BCSC population within tumor tissues." (PMID 39516821, 2024). "Here, we show that YAP directly activates transcription of the “don’t eat me” signal CD24, and plays a crucial role in driving tumor cells to avoid phagocytosis by macrophages." (PMID 38168654, 2024). "The results showed that CD24 expression was closely related to histological type (P = 0.045), primary tumor classification (P = 0.014) and TNM stage (P = 0.032)." (PMID 38914670, 2024).
tumor (continued). "CD24 has also been shown to play a role in tumor initiation, as CD24-positive cells have been shown to have increased tumorigenic potential in animal models." (PMID 38881902, 2024). "Thirdly, CD24 significantly affects the growth of tumor cells by altering the expression of crucial signaling molecules." (PMID 38313430, 2023). "CD24 signaling is reported to promote immune evasion and tumor progression, yet this pathway is also thought to suppress autoimmunity through down regulation of DAMP signaling." (PMID 37346042, 2023). "BCSC populations were more prevalent in TNBC, while differentiated tumor cells (ALDH-non-CD44+CD24-/low) were primarily found in Luminal A and HER2amp cells." (PMID 37771376, 2023). "Breast CSCs are distinguished by their CD44+/CD24- phenotype and can generate circulating tumor cells, thereby facilitating tumor invasion and metastasis." (PMID 38273859, 2023). "In fact, mice treated with LNPs generating CAR-Ms as well as CD24-Siglec-G blockade are able to augment the phagocytic function of liver macrophages, reduce tumour burden and increase the survival of mice subjected to an orthotopic HCC model." (PMID 37894344, 2023). "The results elucidated a crucial role of CD24 in tumor immunosuppression via interaction with Siglec‐10, which acts as a “don't eat me” signal." (PMID 36866919, 2023). "CD24 is highly expressed on tumor cells and it binds to sialic acid-binding Ig like lectin 10 (Siglec10) to inhibit the clearance of tumor cells." (PMID 37834319, 2023). "Our findings demonstrate that the humanized anti-CD24 mAb IMM47 exhibits exceptional anti-tumor activity by blocking the CD24/Siglec-10 interaction through macrophage antigen presentation." (PMID 37846296, 2023). "The interaction between CD24 on cancer cells and Siglec‐10 on macrophages inhibits the phagocytosis of tumor cells by macrophages." (PMID 36866919, 2023). "Using the setup described here with individual tumor cells, we showed that interactions between CD24 on tumor cells and P-selectin expressed on mesothelial cells facilitates tethering and rolling under shear stress." (PMID 36875739, 2023). "(C) Dendritic cells (DCs) (CD45+, CD11c+, MHCIIhigh, F4/80-, CD24+) from liver and peritoneal tumours were analysed by flow cytometry." (PMID 36656749, 2023). "CD24, a heavily glycosylated glycosylphosphatidylinositol‐anchored surface protein, interacts with Siglec‐10 to modulate the tumor immune response." (PMID 36866919, 2023). "In a recent report, downregulation of CD24 in CRC by RNA interference or anti-CD24 monoclonal antibodies significantly inhibited tumor development in vitro and in vivo." (PMID 37919766, 2023). "By inhibiting the connection between CD24 and Siglec-10 using monoclonal antibodies (mAbs), the tumor is effectively phagocytosed." (PMID 37822610, 2023). "Recently, the interaction of CD24 and Siglec-10 was recognized to promote immune evasion of cancer cells, and anti-CD24 antibody inhibited tumor growth by substantially increasing the phagocytosis of cancer cells by macrophages." (PMID 37894750, 2023). "Expression of proliferation marker Ki76, transcription factor TP63, cytokeratin CK20, and cell surface marker CD24 clearly differed in these different tumor cells upon expansion in BME when compared to cells in GD." (PMID 37626918, 2023). "In another study, researchers developed CAR‐NK‐cells targeting both CD24 and mesothelin which simultaneously directs ovarian CSCs and non‐stem cell tumor cells efficiently." (PMID 37698048, 2023). "The levels of CD44+/CD24-cell enrichment on rough surfaces were equivalent to those in tumor spheroids, supporting relevant enrichment levels of the CSC phenotype." (PMID 36968199, 2023). "This innate immune checkpoint, CD24-Siglec10, can be utilized to regulate macrophage-mediated anti-tumor immune responses in drug development." (PMID 37484024, 2023).
tumor (continued). "CD24-targeted therapies, including monoclonal antibodies, ADCs, and cellular immunotherapy, have shown promising anti-tumour activity in preclinical studies." (PMID 38137380, 2023). "The bispecific antibody cG7-MICA targets both the natural killer (NK) cell receptor NK group 2, member D (NKG2D) ligand MHC class I-related chain A (MICA), and CD24, which reduces tumor volume and improves survival rates in Huh-7-bearing nude mice." (PMID 37894750, 2023). "In fact, tumour‐expressed CD24 promoted immune evasion through its interaction with the inhibitory receptor sialic‐acid‐binding Ig‐like lectin 10 (Siglec‐10), expressed by M2‐like TAMs." (PMID 37654003, 2023). "In the world, several active oncology clinical trials were registered on ClinicalTrials.gov to evaluate the efficacy of anti-CD24 based tumor therapy in preclinical models at the time of manuscript writing." (PMID 37919766, 2023). "Here, we characterise the combined role of EpCAM and CD24 in marking a population of disseminating tumour cells in human OSCC specimens." (PMID 37975646, 2023). "Based on above evidences, we had a strong desire to investigate the effects of the BCSC population with CD79A+ and CD24- on tumor immune microenvironment." (PMID 38066053, 2023). "In existing studies on blocking the CD24-Siglec10 axis, anti-CD24 antibodies have been shown to effectively block the CD24-Siglec10 signaling pathway and activate the ability of macrophages to phagocytize tumor cells." (PMID 37484024, 2023). "CD24 immunostaining of colon tissue revealed that the tumour epithelium’s staining pattern comprised the plasma membrane, cytoplasm and nucleus." (PMID 38137380, 2023). "CD24 is a multifunctional molecule, with a wide distribution in diverse cell lineages including tumor cells and immune cells." (PMID 37346042, 2023). "Single cells co-expressing EpCAM, Vimentin and CD24 were abundant in the stroma surrounding metastatic tumours." (PMID 37975646, 2023). "It was identified that sialyl-Lewis x (SLex) carbohydrate is required for CD24-mediated rolling on P-selectin, prompting the migration and dissemination of CD24-expressing tumor cells." (PMID 37919766, 2023). "During the investigation, CD24 was found to be highly expressed universally in various tumours, its glycosylation patterns were very different in cancer cells and normal cells, and CD24 was increasingly correlated with CSCs." (PMID 38137380, 2023). "Additional studies are needed to understand how CD24-Siglec pathway regulates tumor microenvironment." (PMID 37228622, 2023). "When CD24-Fc was used at the onset of vaccination, it appeared to have dampened the anti-tumor efficacy of the cancer vaccine." (PMID 37346042, 2023). "The CD24 expression in tumor cells is related to alterations in multiple oncogenic signaling pathways, including Src/STAT3, EGFR, WNT/β-catenin, and miRNA-related pathways." (PMID 37359556, 2023). "The frequency of CD47+ cells was higher within the double positive (EpCAM+CD24+) tumor cell population than in the EpCAM+CD24- tumor cell fraction in both the spheroids and the tumoroids." (PMID 37876933, 2023). "In conclusion, CD24 is a cell surface protein involved in critical interactions with various receptors, impacting immune regulation, bone health, and tumor immune evasion." (PMID 38313430, 2023). "Engineered T cells specific for CD24 slow tumor growth and prolong survival in SCID mice xenografted with human pancreatic carcinoma." (PMID 37894750, 2023). "Siglec-G is expressed on the surface of macrophages and interacts with the anti-phagocytic signal protein CD24 upregulated in the tumour tissues of HCC patients." (PMID 37894344, 2023). "Consistent with the previous set of tumours, only EpCAM+Vim+CD24+ cells were specifically enriched in the stroma of metastatic tumours." (PMID 37975646, 2023).